RNU6-508P (RNA, U6 small nuclear 508, pseudogene)
Gene: Small nuclear RNA gene on chromosome 2 (59,647,621 to 59,647,723, forward strand). Ensembl gene ENSG00000200101.
Homologues: Orthologues: chimpanzee U6 (100% identical), macaque U6 (99% identical), pig U6 (72% identical), guinea pig U6 (65% identical), mouse Gm24393 (65% identical). Paralogues in human: RNU6-181P (82% identical), RNU6-196P (82% identical), RNU6-639P (82% identical), RNU6-1031P (81% identical), RNU6-1145P (81% identical), RNU6-1209P (81% identical), RNU6-310P (81% identical), RNU6-434P (81% identical), RNU6-658P (81% identical), RNU6-836P (81% identical), RNU6-940P (81% identical), RNU6-106P (80% identical), and 1286 more.